OR52N5 (olfactory receptor family 52 subfamily N member 5)
Description:
Odorant receptor.
Synonyms: OR52N5Q; OR11-62
Tractability: Antibody: UniProt places it where antibodies can reach, with medium confidence; UniProt predicts a signal peptide or a membrane-spanning region; its Gene Ontology location is reachable by antibodies, with medium confidence.
Gene: Protein-coding gene on chromosome 11 (5,776,165 to 5,783,355, reverse strand). Ensembl gene ENSG00000181009.
Subcellular location: Cell membrane
Pathways (Reactome):
Sensory Perception: Expression and translocation of olfactory receptors
Gene Ontology:
Molecular function: olfactory receptor activity; G protein-coupled receptor activity
Biological process: detection of chemical stimulus involved in sensory perception of smell; G protein-coupled receptor signaling pathway; nervous system process
Cellular component: plasma membrane; membrane
Genetic constraint (gnomAD): Loss-of-function variants: 4 observed, 10.41 expected, observed/expected ratio (o/e) 0.38, 90% interval 0.19 to 0.88. The upper end of that interval is the gene's LOEUF score, 0.88, which puts it in group 3 of 6, group 1 being the genes least tolerant of losing a copy. Missense variants: 297 observed, 336.45 expected, observed/expected ratio (o/e) 0.88, 90% interval 0.8 to 0.97. Synonymous variants: 101 observed, 119.83 expected, observed/expected ratio (o/e) 0.84, 90% interval 0.72 to 0.99.
Homologues: Orthologues: chimpanzee OR52N5 (88% identical), rabbit OR52N5 (85% identical), mouse Or52n5 (85% identical), macaque OR52N5 (84% identical), tropical clawed frog or52ak1b (48% identical), tropical clawed frog or52ak1a (47% identical), tropical clawed frog or52k1 (47% identical), tropical clawed frog or52ak1 (46% identical). Paralogues in human: OR52N2 (71% identical), OR52N1 (68% identical), OR52N4 (67% identical), OR52A5 (49% identical), OR52E4 (49% identical), OR52E8 (48% identical), OR51F2 (48% identical), OR52B2 (48% identical), OR52E6 (48% identical), OR52J3 (48% identical), OR52K1 (48% identical), OR52L1 (48% identical), and 39 more.
Diseases named in the same sentence as OR52N5 in open-access papers:
OR52N5 is named in the same sentence as 1 disease in open-access papers, as found by Europe PMC text mining. Sharing a sentence is not in itself a finding about the gene and the disease.
OR52N5 shares sentences with these, for which no sentence is quoted: cancer (1 paper).